CXCL10 (C-X-C motif chemokine ligand 10)
Diseases named in the same sentence as CXCL10 in open-access papers (continued):
Sharing a sentence is not in itself a finding about the gene and the disease.
infection (continued). "CXCL10 binds to the chemokine receptor CXCR3, which is expressed by Th1 cells, and induces lymphocytes to migrate to the infection site, causing lymphatic infiltration and local immune response." (PMID 36034715, 2022). "To date, several CXCL10 from different fish species have been identified, and their mRNA expression levels before and after pathogen infection were determined." (PMID 35795684, 2022). "Most noticeably, Nsp1-K164A/H165A infection had least effects on the expressions of proinflammatory markers, such as Mx2, Ifit3, Tlr6, Cxcl10, and Nfkb1." (PMID 36357440, 2022). "NF-κB activation was equally important for the expression of the chemokine CXCL10 induced by HAdV5 infection in kidney epithelium-derived cells." (PMID 35458402, 2022). "Our lab has previously shown that induction of CXCL10 expression following experimental infection of mice with a neuroadapted strain of murine coronavirus is critical in host defense and acts by attracting virus-specific T cells into the CNS (22, –, 24)." (PMID 34935438, 2022). "This was paralleled by an increase of chemokines (CCL-2, CCL-5, CXCL-10, IL-8) to attract immune cells to the site of infection, contributing to inflammation and tissue damage." (PMID 35788177, 2022). "The increase of IP-10/CXCL10 over time was shown also in an experimental model, showing significantly increased levels in the brain starting from day 5 post infection." (PMID 35918749, 2022). "STING knockdown using siRNA resulted in decreased expression of immune genes such as IFNβ and CXCL10 24 and 48 h post-D2C infection." (PMID 36514984, 2022). "Infection also resulted in the increased expression of CXCL10 and CXCL11 by multiple cell subsets, including goblet 2 cells." (PMID 35038898, 2022). "In correlation with the RNA transcriptomics data, we observed a large increase in CXCL10 upon infection on both the apical and basolateral side of cultures in group high but not in group low." (PMID 35532162, 2022). "Our analyses indicated that despite the presence of baseline inflammation, 2 year old mice had significantly lower induction of innate immune genes at 2 days post-infection, including Il6, Ccl4, Cxcl10, Rig-I, Irf7, Ifna2, Oas1b, and Mx2." (PMID 36415465, 2022). "Further, patients with HEV genotype three infections (clade efg) suffer from severe clinical representations, accompanied by higher CXCL10 serum levels and liver necro-inflammatory activity." (PMID 36366543, 2022). "Changes in the expression of multiple genes, such as CD14, INFB1, and CXCL10, varied with the infection duration." (PMID 36296238, 2022). "During peripheral infection in ganglia, the CXCL10/CXCR3 signaling pathway is indispensable for recruitment of HHV-specific CD8+ T cells and IL-15 plays an essential role in selectively activating these cells." (PMID 35337341, 2022). "Previous studies have shown significantly higher concentrations of IFNα, IL-2, IL-6, IL-12p70, CXCL10, and GM-CSF in patients with a clinical diagnosis of prolonged post-infection fatigue (>6 months) reporting a history of symptomatic WNV infection." (PMID 35458486, 2022). "Quantitative analysis revealed significant levels of the pro-inflammatory cytokines TNFα, IFNγ, and CXCL10 at day 6 after Att-S74-T3Bo infection compared to uninfected control animals." (PMID 36466866, 2022). "Increased cytokines and chemokines such as IL-6, GM-CSF, IL-1a, IL-15, CXCL9 and CXCL10 and complement system components such as C3 were also observed from 6 to 36 months after infection in patients with chronic disease compared to with retrieved controls." (PMID 36189282, 2022). "Following infection with either virus, the effect of Ddx50 KO on Cxcl10 expression, although significant, was less pronounced in comparison to Isg56 and Ifnb." (PMID 35215908, 2022).
infection (continued). "These alterations in the kinetics of monocytes, neutrophils, and CD4+ T cells coincided with a significant increase in serum concentration of TNFα, IFNγ, CXCL10, and IL-10 early after infection." (PMID 36466866, 2022). "Cells of the adaptive immune system such as activated T-helper type 1 (Th1) lymphocytes express CXCR3, the receptor for CXCL10, and they are recruited to the sites of infection/inflammation at least in part by CXCL10-secreting myeloid cells." (PMID 36369044, 2022). "In post-infection treatment, 4OI was somewhat less effective, and itaconate reduced CXCL10 expression only at the higher dose." (PMID 35025971, 2022). "The proinflammatory chemokines CCL3, CXCL3, and CXCL10 were also upregulated following infection, while synapse-related genes, including C1QL1 and SYPL1, were downregulated." (PMID 36314791, 2022). "The production of CXCL10, which has mononuclear cell chemotactic activity, was also upregulated during early infection in this study." (PMID 36352407, 2022). "In this experiment, we furthermore observed that the 6 h pre-incubation was sufficient to induce a significant down-regulation of CXCL10, but that the subsequent 12 h post-infection/stimulation treatment clearly amplified the effect." (PMID 35025971, 2022). "Cytokines in the brain (TNF-α, CCL-2, CXCL-2, CXCL-10, IL-1β, IL-6, IL-17, and M-CSF) were upregulated after infection at 3 dpi, and the cytokine content gradually decreased with extension of the infection time." (PMID 36352407, 2022). "At day 6 after infection, expression levels of chemokines, including CXCL10 and CCL2 and CCL-3 were elevated by more than 300-fold." (PMID 35215199, 2022). "Infection led to robust induction of chemokine and interleukin genes, including Il1b, Il6, Ccl2, Ccl3, Ccl4, Ccl7, Cxcl1, Cxcl2, Cxcl5, Cxcl9, and Cxcl10, and related receptor genes, including Ccr1, Ccr4, Ccr5, Ccr5, Ccr7, Cxcr2, Cxcr5, Il1r2, and Il1rn." (PMID 35487885, 2022). "CXCL10 is a primary IFN-γ-inducible immunomodulatory cytokine with a role in homing activated Th1 CD4+ T cells to sites of infection or inflammation." (PMID 35743825, 2022). "While CXCL10 helps to promote leukocyte trafficking to the site of infection to generate an inflammatory immune response, it has been shown to cause neurotoxicity." (PMID 35744680, 2022). "Our data suggests that CXCL10 is produced by stimulated adaptive NK cells, thus possibly recruiting more of Th1 cells to the site of infection." (PMID 35177828, 2022). "The mutant strain stimulated BV2 cells to produce fewer inflammatory factors, such as iNOS and CXCL-10, than the wild-type strain after infection." (PMID 36352407, 2022). "Cxcl10 was found to be elevated in all tissues at day 7 post-infection, consistent with its induction by IFN." (PMID 33524035, 2021). "In response to H1N1 or H3N2, there was a marked elevation of Ccl3, Ccl4, Ccl5, and Cxcl10 in young lung at day 3 post infection." (PMID 34829979, 2021). "Nevertheless, the RNA levels of IL-6, CCL2 and CXCL10 decreased after 5 days of infection, especially IL-6 that went down with more than 5-fold reduction compared to that on day 2 post infection." (PMID 34379705, 2021). "We again assessed changes in host gene expression by RNA-sequencing, and observed a reduction of mRNA levels of various genes induced by the infection, including the cytokines CXCL10 and CXCL11." (PMID 33585804, 2021). "The intensive care unit stay, the hemodynamic instability, the cause of death, the presence of risk factors for cardiovascular disease and the presence of ongoing infection resulted as significant determinants of IL-6 and CXCL10 donor concentrations." (PMID 33758270, 2021). "The results of IL-6, CCL2 and CXCL10 secretion from OT-infected HMECs at 8, 16, 24, and 48 hours post-infection were shown in." (PMID 34368012, 2021).
infection (continued). "More importantly, we found that such TNFα-mediated enhancement during infection was 2- to 3-folds reduced in Mincle-/- MΦs (Il27, Cxcl10, Ccl2), implying the mitigation of proinflammatory responses." (PMID 34320039, 2021). "An example of an elevated plasma protein at infection is the chemokine CXCL10 which is involved in the stimulation of monocytes, natural killer and T-cell migration." (PMID 34844191, 2021). "When quantifying the cytokine profiles in BALs from mock control and RSV-infected animals, the most noticeable induction upon infection were IL-10 (day 6 p.i.), IL-8 and CXCL10/IP-10 (days 3 and 6 p.i.)." (PMID 33909707, 2021). "Genes encoding interferons (Ifnb, Ifnl2 and Ifnl3), chemokines (Ccl7, Ccl5, and Cxcl10), and ISGs (Ifit1, Ifit2, Ifit3b, Oas3, Ifi44, Rsad2, and Isg15, among others) were prominently represented among those induced by infection in Ifnar1-/- mice." (PMID 34591933, 2021). "(C) Plasma concentration of interferon alpha and gamma and interferon-stimulated chemokines (CXCL9 and CXCL10) during infection." (PMID 33648633, 2021). "We were intrigued to observe that infection of SK-N-SH cells with both ZIKV strains in the presence of 50 μM LXR 623 resulted in significantly higher mRNA expression levels for CXCL10, CCL5 / RANTES and IFN-β1." (PMID 34162308, 2021). "CXCL10 is chemotactic for macrophages and thus enhances the innate immune response to infection, and is part of the inflammatory response to injury." (PMID 33657181, 2021). "At 24 hr post-infection, we observed significant increases in WT production of Il27, Cxcl10, and Cxcl9, which were diminished in Mincle-/- cells." (PMID 34320039, 2021). "There was a robust correlation between SARS-CoV-2 transcripts and the IFN-γ-induced chemokine Cxcl-10 (IP-10) and to a lesser extent Csf1, Ccrl2, and Ccl5, which are all involved in the recruitment of immune cells to the site of infection." (PMID 34319784, 2021). "Proteins highlighted in green (e.g., CCL2=MCP-1, CCL7=MCP-3, CCL8=MCP-2, CXCL10=INP10, are proteins known to be elevated in blood after infection for example with M. tuberculosis." (PMID 35145507, 2021). "During CT, CXCL9 and CXCL10, among others, play important roles in recruiting T cells and macrophages into the brain to maintain the latency of infection." (PMID 34262559, 2021). "Pulmonary arterial endothelial cells responded most rapidly to infection, with high expression of Cxcl10, Tnfsf10, and Ccl7 by 2 dpi." (PMID 34381043, 2021). "At the peak of arthritic disease, which occurs 6 to 8 days post infection in mice, CXCL10−/− mice had decreased levels of immune infiltration as well as viral loads at the site of viral inoculation, the footpad, compared to wild-type mice." (PMID 34073501, 2021). "(D) Plasma concentration of CXCL10 and IFNɣ during the acute phase of first (n = 4) or second (n = 5) infection (box-plots show median and IQR)." (PMID 33752799, 2021). "The ability of HMECs to secrete CXCL10 after OT infection was just slightly lower than that of monocytes." (PMID 34368012, 2021). "Protection against lethal infection; reduced granulocyte recruitment; reduced expression of proinflammatory cytokines CXCL10, CXCL1, CCL2, and TNF." (PMID 34557097, 2021). "The CXCL10 level constantly increased from 8 to 24 h post-infection and was persistent at the late stage of infection." (PMID 34368012, 2021). "When the infection becomes severe (as in the case of CM), CXCL10 secretion reaches high levels despite this parasitic effect." (PMID 34381047, 2021). "This outcome provides extended evidence about the functional involvement and significant contribution of ACE2 and CXCL10 to the SARS-CoV-2 mediated infection development." (PMID 33585826, 2021). "Host control of inflammation extended beyond the boundaries of the spleen with circulating levels of CXCL10 and IFNɣ also attenuated at the peak of second infection." (PMID 33752799, 2021).
infection (continued). "The predominant populations in the infiltrates were macrophages and neutrophils in the wild-type mice following infection but this influx was significantly reduced in the CXCL10−/− mice." (PMID 34073501, 2021). "The differences in Il27 and Cxcl10 production in infected Mincle-/- and WT cells was even more pronounced by 24 hr post-infection." (PMID 34320039, 2021). "At week 2 post-infection, expression levels of Cxcl10 and Cxcl11 tended to be higher in vaccinated C57BL/6 and IL-23p19−/− mice and were even significantly increased in vaccinated IL-17A−/− mice when compared to the respective unvaccinated control group." (PMID 34351501, 2021). "We found that bystander cells from H. hammondi-infection had significantly higher CXCL10 transcript as compared to those from mock infection (by ~10-fold), and RT-qPCR for H. hammondi GRA1 transcript confirmed the absence of parasites in the bystander cells." (PMID 32574210, 2020). "In chronic HBV, serum and intrahepatic CXCL10 concentrations increase during HBV flares and correlate with HBV DNA, alanine aminotransferase (ALT) and progressive liver disease; and elevated CXCL10 in blood is found in HIV mono-infection compared to controls." (PMID 32898182, 2020). "In our study, reduced expression of IFNγ, LTα, ICAM-1, CXCL9 and CXCL10 were in line with impaired recruitment of CXCR3+CD8+ T cells to the brains of mice that received BCG before PbA infection." (PMID 33316929, 2020). "We found a marked upregulation of IFN-β, IFN-λ1, IFN-λ2/3, CXCL8, and CXCL10 in basolateral medium samples upon RSV infection compared to mock infection, starting from 24 to 48 hpi." (PMID 32878928, 2020). "To confirm the impact of HIV infection on CXCL10 production, we repeated the infections in the presence of antiretroviral agents." (PMID 32898182, 2020). "Further, in vitro infection of human type II alveolar epithelial cells maintained at an air-liquid interface led to productive virus replication and significant upregulation of CXCL10 and CXCL11, as well as CXCL8 and the Th1 cell-directed chemokine CCL5." (PMID 33613280, 2020). "Elevated levels of CXCL10 in plasma early in infection have been reported to be a particularly poor prognostic indicator." (PMID 33613280, 2020). "We demonstrated that CXCL10 production from hepatocytes increases following direct infection with HIV." (PMID 32898182, 2020). "Contrasting results were observed in a study which reported a comparatively higher innate immune response to YF-17D than Asibi, but that study measured chemokines (CCL5, CXCL10) instead, which act by attracting phagocytic cells to sites of infection." (PMID 32722523, 2020). "The chemokines CXCL2, CXCL3 and CXCL10 are part of “the immune response” pathway, which is highly upregulated following basolateral infection compared to control, as shown in the gene set enrichment analysis (GSEA)." (PMID 32872518, 2020). "A similar suppression was observed in LCLs, where infection with RST17 (CPAF-) led to 295 pg/ml (107%) more CXCL10 on average for three LCLs compared to the RST5 (CPAF+) infection." (PMID 33106516, 2020). "Differences in mRNA expression of IFNs and CXCL10 revealed species-specific expression patterns across the time course of infection." (PMID 32226041, 2020). "The results show that the viremia of Cxcl10−/− mice were comparable to those in WT mice at days 2 and 4 post infection (p.i.), suggesting that CXCL10 is dispensable for controlling the systemic dissemination of CHIKV." (PMID 33147869, 2020). "Macrophages constituted the largest immune cell population in footpads following infection, and were significantly reduced in Cxcl10−/− mice." (PMID 33147869, 2020). "K18-hACE2 SARS-CoV-2 infected mice showed elevated levels of Il6, Ccl2, and Cxcl10 at day 2 post-infection, which returned to baseline by day 5 post-infection." (PMID 33073694, 2020).
infection (continued). "We found that compared to wild type T. gondii (RH strain), prior infection with T. gondii ΔIST parasites was significantly less effective at suppressing H. hammondi-mediated CXCL10 production." (PMID 32574210, 2020). "Following USUV infection, we showed secretion of CXCL10, CCL5, and IL6 in apical compartments from 4 to 10 dpi, but the secretion level decreased with time." (PMID 32324736, 2020). "Overall, our results demonstrate that CPAF suppresses CXCL10 to evade the host cytokine response and that modeling of cellular infection parameters can reveal previously unrecognized facets of host–pathogen interactions." (PMID 33106516, 2020). "Transcripts of Ifnb (A) or ISGs (Cxcl10, Isg20, Ccl5, Isg15) (B) were determined 6 hr after infection." (PMID 32886065, 2020). "We found that TgVEG infection significantly and dramatically suppressed H. hammondi-mediated CXCL10 secretion." (PMID 32574210, 2020). "The CXCL10 expression by MO-DCs and pDCs started very early and remained until day 20 after infection, which is consistent with the high expression of CXCR3 in specific CD8+ T cells, observed from day 5 to 30 after infection." (PMID 32574175, 2020). "Transcripts of Ifnb (B) or ISGs (Cxcl10, Isg20, Ccl5, Isg15) (C) were determined at 6 hr after infection." (PMID 32886065, 2020). "Dose–response curves demonstrated that while cpa::cat LGV-L2 infection of LCLs have increasing CXCL10 induction with higher MOI, WT LGV-L2 showed greater suppression at higher MOI." (PMID 33106516, 2020). "The chemokines CXCL9 and CXCL10 are expressed constitutively by airway epithelium and increase during infection." (PMID 32817719, 2020). "The chemokine CXCL10 (IP-10) plays a deleterious role in infection and inflammation by activating the chemokine receptor CXCR3, an important regulator of lymphocyte trafficking and activation." (PMID 32973504, 2020). "The mRNA expression of IFNs revealed antagonism of type I and III IFNs and a significant increase in the chemokine, CXCL10, in bat lung and spleen following infection." (PMID 32226041, 2020). "Instead, linear modeling of the detailed infection parameters collected during the cellular GWAS of CXCL10 supported a model of bacterial suppression of chemokine levels." (PMID 33106516, 2020). "We observed a strong inflammatory gene signature in isolated monocytes during subpatent infection, including increased CXCL10, CXCL9 and STAT1 gene expression." (PMID 32566226, 2020). "Third, we considered cell death at 70 h post infection to account for decreased CXCL10 due to a lower number of viable cells." (PMID 33106516, 2020). "We noted a strong upregulation of genes encoding for CXCL2, CXCL3, CXCL10, IFNβ-1, IFNλ-1, -2, -3, endothelin 1 (EDN1) and IFIT-1, -2, -3 following E-30 infection." (PMID 32872518, 2020). "IL-1β (P < 0.05) and CXCL10 (P < 0.05) were both significantly but modestly reduced in the KO animals on day 4 after infection." (PMID 32611756, 2020). "CXCL10 is a pro-inflammatory Th1-chemokine driving migration to the site of infection of Th-1 T-cells, monocytes and neutrophils that express its receptor CXCR3." (PMID 33272291, 2020). "Serum CXCL10 levels increase with SARS disease progression independently of secondary infection, and only wane during convalescence." (PMID 33613280, 2020). "(C) Fold induction of CXCL10 after infection of THP-1 cells with HIV-GFP -Vpr or HIV-GFP +Vpr at the indicated MOI." (PMID 33300875, 2020). "GEM treatment (100 μM) of BMDMs dramatically suppressed the expression of a variety of inflammatory cytokines and chemokines (Il6, Il12p40, Il1b, Cxcl10, and Cxcl5) at 18 h after infection." (PMID 32155958, 2020). "Similar results were observed for CXCL10 level, which peaked at 7 dpi in the Placebo group and was still significantly higher at 10 dpi than before infection (76.3 ± 7.1 and 16 ± 2.4 pg/ml, respectively)." (PMID 32194549, 2020).